BAK1 (BCL2 antagonist/killer 1)
Diseases named in the same sentence as BAK1 in open-access papers (continued):
Sharing a sentence is not in itself a finding about the gene and the disease.
ovarian carcinoma (6 papers, 2014 to 2023). A malignant neoplasm originating from the surface ovarian epithelium. "As a general tendency, PCR studies showed an upregulation of p21 and of proapoptotic genes APAF1, PUMA, BAK1 as well as a downregulation of the antiapoptotic gene survivin (BIRC5) in ovarian cancer cell lines." (PMID 31234549, 2019). "On the other hand, Kong and colleagues reported an upregulation of miR-125 in ovarian cancer and suggested that up-regulation of miR-125b expression contributes to cisplatin resistance through suppression of Bak1 expression." (PMID 27092777, 2016). "Overexpression of miR-125b enhanced resistance of ovarian cancer cells to cisplatin by targeting Bak1." (PMID 24788655, 2014). "Current knowledge of ovarian cancer provides strong indications that not only establish BOK as an inducer of apoptosis in a BAX- and BAK1-independent manner, but also suggest that BOK can significantly influence the apoptotic response to chemotherapeutic drugs in ovarian carcinoma cells." (PMID 37888203, 2023). "These literature results prompted us to analyze the gene expression profile of the five apoptosis and survival-related genes APAF1, survivin, BAK1, p21, and PUMA by PCR in all ovarian cancer cells used in this study under single and combination treatments of HDACi with cisplatin." (PMID 31234549, 2019).
viral infection (6 papers, 2016 to 2025). "In fact, members of the SERK family, particularly SERK1 and BAK1, have also been implicated in regulating plasmodesmata permeability and immune signaling during viral infections." (PMID 41334200, 2025). "The map illustrates that HSPA8 and proteins in subnetworks, such as EIF2AK3, TLR4, NFKB1, BAK1, and RelA, are enriched in viral infection of several viruses." (PMID 34769416, 2021). "In contrast, BAK1 tended to be up-regulated by the viral infections, although a significant overexpression occurred only in BBP+/FN plants showing RN (1.4 l2fc), as compared to BBP+/FN showing DN (0.8 l2fc)." (PMID 28182745, 2017). "Only BAK1 showed no expression variations upon viral infections in BB plants." (PMID 28182745, 2017). "In the absence of bacterial and viral infection, NIK1 is bound to FLS2 and BAK1 to prevent activation of an autoimmune response." (PMID 31676803, 2019). "These include the co-receptor SERKs, BAK1 and SERK1, and the MAPK4 negative regulator, in addition to common effects of non-viral PTI that are also elicited during virus infection." (PMID 28105028, 2016).
acute myocardial infarction (5 papers, 2013 to 2024). Necrosis of the myocardium, as a result of interruption of the blood supply to the area. "Cardiomyocytes overexpressing miR-125b-5p have increased prosurvival signaling and protected the heart from acute myocardial infarction by repressing pro-apoptotic bak1 and klf13." (PMID 30717412, 2019). "In addition, BAK1 has shown essential functions in cardiovascular diseases such as acute myocardial infarction." (PMID 34238204, 2021). "miRNA-125-5p could protect the heart against acute myocardial infarction by inhibiting the expression of pro-apoptotic factors BAK1 and KLF13 in cardiomyocytes." (PMID 34238204, 2021). "Finally, and consistent with results in DKO MEFs, cardiac-specific deletion of Bax/Bak1 significantly protected the heart from ischemia–reperfusion (I-R) injury and reduced lethality in mice subjected to permanent myocardial infarction injury." (PMID 23991283, 2013). "It was noted that some key genes involving PAMPs (pathogen-associated molecular patterns) were also identified, including FLS2, BAK1, CDPK9 and SERK4, suggesting that the basic defense response were inspired in Cm response to Mi infection." (PMID 28615634, 2017).
colon carcinoma (5 papers, 2018 to 2023). "Pyroptosis in colon cancer cell lines can be mediated by BAK1 or BAX alone, and caspase 3 activity is required in BAK/BAX-mediated pyroptosis." (PMID 37337018, 2023).
germ cell tumor (5 papers, 2013 to 2022). A benign or malignant, gonadal or extragonadal neoplasm that originates from germ cells. "Several top SNPs (FDR < 0.05) also map to the region adjacent to the classical HLA class II region (e.g., IP6K3 (associated with educational attainment and phosphorus levels) and BAK1 (associated with platelet count, chronic lymphocytic leukemia, and testicular germ cell tumor))." (PMID 29309429, 2018). "Recent advances have implicated the KITLG/SPRY4/BAK1 and TGFβ/BMP-signaling (BMPR1B) pathways in germ cell tumor development, which include the control of differentiation, cell proliferation and apoptosis." (PMID 23599692, 2013). "Similarly SNP, in or near BAK1, prompted the occurrence of testicular germ cell tumor." (PMID 25186767, 2014).
non-small cell lung carcinoma (5 papers, 2008 to 2023). A group of at least three distinct histological types of lung cancer, including non-small cell squamous cell carcinoma, adenocarcinoma, and large cell carcinoma. "The researchers discovered a failure to inhibit ES-induced death of non-small cell lung cancer A549 cells and NCIH2030 cells using all known inhibitors of cell death modalities after targeted knockdown of the BCL2-Associated X (BAX) and Recombinant Bcl2 Antagonist/Killer 1 (BAK1) genes." (PMID 38023234, 2023).
chronic lymphocytic leukemia (4 papers, 2015 to 2024). "This integrative analysis identified genes whose dysregulation may explain the links between JIA and associated traits, such as autoimmune/inflammatory diseases (genes at 6p22.1 locus), Hodgkin lymphoma (genes at 6p21.3 [FKBPL, PBX2, AGER]), and chronic lymphocytic leukemia (BAK1)." (PMID 39175752, 2024). "Notably, in addition to HLA class II genes (which might contribute to chronic inflammation), we found a distinct association between JIA and Hodgkin lymphoma through a set of genes in 6p21.3 (FKBPL, PBX2, AGER); and chronic lymphocytic leukaemia through the BAK1 gene." (PMID 39175752, 2024).
neuroblastoma (4 papers, 2011 to 2021). Neuroblastoma (NB) is the most common solid, extracranial childhood tumor. "In mouse N2A neuroblastoma cells, miR-125b significantly downregulated mouse BAK1, PPP1CA, PUMA, and ITCH protein." (PMID 21935352, 2011).
osteosarcoma (4 papers, 2021 to 2025). A usually aggressive malignant bone-forming mesenchymal neoplasm, predominantly affecting adolescents and young adults. "The treatment upregulated cleaved caspase-3, cleaved caspase-9, phosphorylated H2Ax, Bax, Bak1, and cytochrome c, while downregulating survivin and Mcl-1 in osteosarcoma cells." (PMID 40535821, 2025). "Through the survival analysis of the single gene, the BAK1, CASP6, and GSDMA were found to be linked to the prognosis of osteosarcoma." (PMID 36244998, 2022). "In addition, TF3 increased the levels of phosphorylated histone H2Ax, Bax, Bak1, and cytochrome c, while reducing the levels of Mcl-1 and survivin in osteosarcoma cells." (PMID 40535821, 2025). "By the Lasso Cox regression analysis, 6 key PRGs were screened for constructing the optimal model, namely CHMP4C, GZMA, BAK1, CASP1, CASP6, and GSDMA, and a six PRGs signature was successfully constructed for osteosarcoma." (PMID 36244998, 2022).
B cell lymphomas (3 papers, 2018 to 2024). "LINC00511 was reported to regulate apoptosis, with anti-apoptotic BRI1-associated kinase 1 (BAK1), which is highly expressed in B cell lymphoma, regulated by CTD-2020K17.1." (PMID 39062113, 2024). "Moreover, CTD-2020K17.1 also regulated the BAK1 gene (F.C. +2.46) that is frequently overexpressed in B cell lymphomas." (PMID 31480511, 2019).
endometrial cancer (3 papers, 2013 to 2023). Primary or metastatic malignant neoplasm involving the endometrium (mucous membrane that lines the endometrial cavity). "Common genetic variants in the BCL-2-family genes BCL2, BAD, BAX and BAK1 were comprehensively evaluated for associations with endometrial cancer risk." (PMID 23637776, 2013). "We investigated whether genetic variants in the BCL-2-family genes BAD, BAX, BCL2 or BAK1 are associated with endometrial cancer risk." (PMID 23637776, 2013). "In endometrial cancer, three differentially expressed ARGs (ERBB2, BAK1 and MYC), which are closely related to the occurrence of endometrial cancer, were increased." (PMID 33109128, 2020).
glioblastoma (3 papers, 2015 to 2017). The most malignant astrocytic tumor (WHO grade IV). "Interestingly, miR-125b inhibitor boosts the chemosensitivity of glioblastoma stem cells to TMZ by targeting Bak1, whereas the miR-128, miR-149 and miR-181 families enhance the chemosensitivity of glioblastoma cells to TMZ by targeting Rap1B." (PMID 25605243, 2015). "Interestingly, studies have identified that inhibition of miR-125b enhanced the chemosensitivity of glioblastoma stem cells to temozolomide through regulating Bak1 (Bcl-2 antagonist killer 1) and PIAS3 (protein inhibitor of activated signal transducer and activator of transcription)." (PMID 25605244, 2015).
melanoma (3 papers, 2019 to 2025). A malignant, usually aggressive tumor composed of atypical, neoplastic melanocytes. "We first generated BAX and BAK (BAX-/-BAK1-/-) knockout and wild-type controls in BRAF(V600E) mutant A375 melanoma cells with CRISPR/Cas9 technology." (PMID 36918588, 2023).
pancreatic cancer (3 papers, 2009 to 2024). "Using univariate Cox regression, a forest map was generated showing seven ARGs associated with pancreatic cancer prognosis: BAK1, ITGA3, BIRC5, WDR45, BAG3, APOL1, and RAB24." (PMID 35488119, 2022). "By contrast, in pancreatic cancer, increased H3K9me3 levels within the BCL2 antagonist/killer 1 (BAK1), BCL2 associated X (BAX), and BLC2-like 11 (BCL2L11) gene promoters were shown to inhibit the expression of these apoptotic effectors." (PMID 39519018, 2024). "QRT-PCR was performed to evaluate the levels Shh, Gli1, IGFBP6, IGF2, PCNA, Bcl-2, Bax and Bak1 mRNA in pancreatic cancer tissues (n = 6) and corresponding cancer side tissues (n = 6)." (PMID 19736394, 2009). "On one hand, Shh-Gli1 signaling acts to inhibit apoptosis of pancreatic cancer cell by directly activating expression of Bcl-2 and indirectly decreasing the levels of Bax and Bak1." (PMID 19736394, 2009). "The expression levels of BAK1, ITGA3, BAG3, and APOL1 were statistically increased in pancreatic cancer samples versus normal samples, while those of RAB24 was decreased." (PMID 35488119, 2022). "BAK1, ITGA3, BAG3 and APOL1 were highly expressed in most pancreatic cancer and pancreatic ductal adenocarcinoma cell lines, while RAB24 was poorly expressed." (PMID 35488119, 2022). "Compared with those from the normal controls, immunohistochemical results from the pancreatic tissues revealed statistical increases in the expression of BAK1, ITGA3, BAG3, and APOL1 in pancreatic cancer patients; no immunohistochemical data were available for RAB24." (PMID 35488119, 2022).
sarcopenia (3 papers, 2020 to 2025). Progressive decline in muscle mass due to aging which results in decreased functional capacity of muscles. "The downregulation of miR-532-3p, an inflammation-associated miRNA, regulates the apoptotic pathway during sarcopenia progression by targeting BCL2 antagonist/killer 1 (BAK1)." (PMID 40678078, 2025). "The downregulation of miR-532-3p abolishes its inhibition of the proapoptotic gene BAK1, causing the activation of BAK1-dependent downstream caspase cascades and eventually leading to apoptosis and the occurrence of sarcopenia." (PMID 32226296, 2020). "Also, miR-532-3p downregulation has been associated with sarcopenia progression though inflammation mediated via BAK1 regulation." (PMID 40678078, 2025). "For example, miR-532-3p targets BAK1 to suppress inflammation and apoptosis signals in human sarcopenia." (PMID 38659023, 2024). "To determine if its protein level was also increased, we measured serum BAK1 level with an ELISA assay using samples from 24 sarcopenia patients and 24 healthy controls." (PMID 32226296, 2020). "Overall, our results uncovered a new mechanism by which the inflammation-dependent downregulation of miR-532-3p contributed to the pathogenesis of sarcopenia through mediating BAK1 expression." (PMID 32226296, 2020). "Our results showed that the circulating BAK1 level in sarcopenia patients was much higher than that in healthy controls." (PMID 32226296, 2020). "Given that BAK1 is a proapoptotic protein and that its induction can result in the activation of downstream caspase cascades, we next sought to determine if apoptotic signaling was activated in the sarcopenia samples." (PMID 32226296, 2020). "In addition, we also examined the BAK1 protein levels in three-paired muscle tissues from sarcopenia patients and healthy controls." (PMID 32226296, 2020). "Our results indicated that BAK1 was significantly increased in the three sarcopenia samples." (PMID 32226296, 2020). "We observed that the expression of IL1B, BAK1 and SOD1 were significantly increased, while the expression of CDH1, GNG11 and ZAP70 were dramatically decreased in sarcopenia samples compared to those in the controls." (PMID 32226296, 2020).
autoimmune disease (2 papers, 2013 to 2014). A disorder resulting from loss of function or tissue destruction of an organ or multiple organs, arising from humoral or cellular immune responses of the individual to their own tissue constituents. "BAK1 was seen to be overexpressed in patients affected with autoimmune disease such as multiple sclerosis, MS." (PMID 25186767, 2014). "BAK1 is a crucial mediator of B-cell death and plays a role in the prevention of autoimmune disease." (PMID 24381713, 2013).
Crohn disease (2 papers, 2018 to 2024). A gastrointestinal disorder characterized by chronic inflammation involving all layers of the intestinal wall, noncaseating granulomas affecting the intestinal wall and regional lymph nodes, and transmural fibrosis. "Some of these traits (i.e., platelet-to-lymphocyte ratio, general cognitive ability) as well as Crohn’s disease are further linked to JIA through the neighbouring cluster 6 genes (HLA-FAS1, BAK1, CLN3, SGF29)." (PMID 39175752, 2024).
cyst (2 papers, 2017 to 2023). A sac-like closed membranous structure that may be empty or contain fluid or amorphous material. "Considering the data from Proteinase K treatment and recently published data on root-knot nematodes, we hypothesized that bak1 mutants would be more susceptible to cyst nematodes." (PMID 28406987, 2017).
dengue (2 papers, 2016 to 2024). "Although the association of the G allele of rs5745568 with low platelet count in patients with dengue remains to be confirmed in future studies, the present results suggest that the BAK protein, encoded by BAK1, plays a crucial role in the pathogenesis of DHF." (PMID 27401010, 2016).
endometriosis (2 papers, 2023 to 2025). The growth of functional endometrial tissue in anatomic sites outside the uterine body. "Compared to normal human endometriosis cells, the expression of BAK1, CHMP2A, GPX4, and GSDMD was upregulated, whereas the expression of CHMP2B, IRF2, and TIRAP was negatively regulated in UCEC cells." (PMID 40535818, 2025).
fungal infection (2 papers, 2023 to 2025). "Intriguingly, flg22-triggered phosphorylation of CERK1 by BAK1 establishes a primed conformation of CERK1 to further respond to fungal infections." (PMID 40508004, 2025).
head and neck squamous cell carcinoma (2 papers, 2021 to 2023). A squamous cell carcinoma that arises from any of the following anatomic sites: lip and oral cavity, nasal cavity, paranasal sinuses, pharynx, larynx, and salivary glands. "An established prognostic signature based on seven genes including BAK1 was able to predict the survival outcome of head and neck squamous cell carcinoma patients." (PMID 34335109, 2021). "Interestingly, ITGA3 was also a component of the prognostic signature for head and neck squamous cell carcinoma, with a similar role like BAK1." (PMID 34335109, 2021). "For example, a study developed a prognostic model based on four cellular senescence-related genes (BAK1, DKK1, CDKN2A, and MIF) to predict the survival rate of individuals with head and neck squamous cell carcinoma." (PMID 37580647, 2023).
nematode infection (2 papers, 2017 to 2021). "In a more recent publication, it was shown that nematode infection triggers PTI responses in Arabidopsis in a BAK1-dependent and BAK1-independent manners." (PMID 28406987, 2017). "A nematode infection assay was performed on bak1-5 and the double mutant bak1-5 bkk1-1 (BKK1 being the closest homolog of BAK1)." (PMID 28406987, 2017).
Pseudomonas infection (2 papers, 2013 to 2022). Infections with bacteria of the genus pseudomonas. "Furthermore, BRI1-ASSOCIATED RECEPTOR KINASE1 (BAK1) protein levels decreased in the mutants compared with that in WT plant in the absence of Pseudomonas infection." (PMID 36523630, 2022). "At2g31880 expression is elicited by flagellin or Pseudomonas infection and activates defence responses through a signalling pathway that is repressed by BIR1, a negative regulator of BAK1." (PMID 23372747, 2013).
Sepsis (2 papers, 2022 to 2023). Sepsis is defined as life-threatening organ dysfunction caused by a dysregulated host response to infection. "Moreover, transcript levels of the pro-apoptotic genes BAK1, CYCS, BBC3, CASP7, and CASP8 were upregulated in the COVID-19 cohort, whereas those of anti-apoptotic genes, such as BCL2L11 and BCL2L1, were upregulated in the sepsis cohort." (PMID 36443881, 2022).
vitiligo (2 papers, 2024 to 2025). Generalized well circumscribed patches of leukoderma that are generally distributed over symmetric body locations and is due to autoimmune destruction of melanocytes. "The 3D‐Exos harboring miR‐132‐3p and miR‐125b‐5p can induce Treg cells differentiation and suppress oxidative stress‐induced melanocyte apoptosis by targeting Sirt1 and Bak1 respectively, ultimately alleviating the progression of vitiligo." (PMID 38887870, 2024).
Alzheimer disease (1 paper, 2024). A progressive, neurodegenerative disease characterized by loss of function and death of nerve cells in several areas of the brain leading to loss of cognitive function such as memory and language. "Increased BAK1 expression has been linked to auditory dysfunction in patients with Alzheimer’s disease." (PMID 38542318, 2024).
Barrett esophagus (1 paper, 2018). Esophageal lesion lined with columnar metaplastic epithelium which is flat or villiform. "Based on previous studies investigating the role of BAK1, FIS1, and SFN, one primary function of these three genes in Barrett’s esophagus and in Barrett’s associated OAC may also be in conferring therapeutic resistance to cells; however, further studies are necessary to explore this relationship." (PMID 30404157, 2018).
cognitive decline (1 paper, 2025). "Our investigations reveal that aging differentially modulates restraint stress-induced ER stress responses: while suppressing the upregulation of protective ER stress-related genes (Fmo2, Creb3l1, Tmtc3, Bak1), it promotes the induction of Pgap1 change associated with cognitive decline." (PMID 41200271, 2025).
Cognitive impairment (1 paper, 2024). Abnormal cognition is characterized by deficits in thinking, reasoning, or remembering. "The predicted expression level of BAK1 is higher in participants with cognitive impairment." (PMID 38542318, 2024).